Y_RNA (Y RNA )
Gene: Miscellaneous RNA gene on chromosome 2 (52,297,995 to 52,298,096, forward strand). Ensembl gene ENSG00000202195.
Homologues: Orthologues: chimpanzee Y_RNA (100% identical), guinea pig Y_RNA (77% identical). Paralogues in human: Y_RNA (81% identical), Y_RNA (80% identical), RNY3P9 (79% identical), Y_RNA (79% identical), RNY3 (78% identical), RNY3P3 (78% identical), Y_RNA (78% identical), Y_RNA (77% identical), Y_RNA (76% identical), RNY3P1 (75% identical), Y_RNA (75% identical), RNY3P14 (75% identical), and 90 more.